FABP5 (fatty acid binding protein 5)
Diseases named in the same sentence as FABP5 in open-access papers (continued):
Sharing a sentence is not in itself a finding about the gene and the disease.
melanoma (6 papers, 2020 to 2025). A malignant, usually aggressive tumor composed of atypical, neoplastic melanocytes. "Studies have demonstrated that FABP5 is upregulated in melanoma and linked to tumor cell proliferation, metabolism, and malignant progression." (PMID 40717587, 2025). "FABP5 exhibits diverse functions in melanoma, with its expression levels closely associated with tumor progression, metastasis, and poor prognosis." (PMID 40717587, 2025). "Insufficient information is available concerning the role of FABP5 in melanomas vs. its association with prognosis." (PMID 32934956, 2020). "Transcription profiles of FABP5, IVL, KRT6A, KRT15, KRT16, and TIMP2 provided clues of prognostic implications, which might help us evaluate malignant potential of nevus and underlying carcinogenesis progress from melanocytic nevus to melanoma." (PMID 32934956, 2020). "Expression profiles of FABP5, IVL, KRT6A, KRT15, KRT16, and TIMP2 provide clues of prognostic implications, which might help us evaluate malignant potential of nevus and underlying carcinogenesis progress from melanocytic nevus to melanoma." (PMID 32934956, 2020). "In terms of prognosis, high expression of FABP5 correlates with shorter overall survival (OS) and poorer progression-free survival (PFS) in melanoma patients." (PMID 40717587, 2025). "Further, alterations in the expression profiles of FABP5, IVL, KRT6A, KRT15, KRT16, and TIMP2 were significantly associated with worse prognosis, indicating that these hub genes may participate in the aggressive transformation from a nevus to malignant melanoma." (PMID 32934956, 2020). "Therefore, to elucidate the unidentified effects of the antidiabetic regents, FABP5, ANGPTL4 and/or MITF on diabetic states of MM, high-glucose-induced metabolic and redox alterations were studied using melanoma A375 cells." (PMID 39940783, 2025). "In addition, survival curves indicated that six hub genes, including FABP5, IVL, KRT6A, KRT15, KRT16, and TIMP2, were significant prognostic signatures for CM and of significant value to predict transformation from nevi to melanoma." (PMID 32934956, 2020). "Urinary excretion of FABP5 is detected in patients with stages II and III cutaneous melanoma but not those with stage IV melanoma." (PMID 32934956, 2020).
pancreatic neuroendocrine neoplasm (6 papers, 2023 to 2026). A neoplasm with neuroendocrine differentiation that arises from the pancreas. "ALKBH5 is highly expressed in pancreatic neuroendocrine neoplasms (pNENs) and promotes the expression of FABP5 by reducing the m6A modification degree of FABP5 mRNA at 5'UTR." (PMID 41522342, 2026). "FABP5 promotes tumor progression in pancreatic neuroendocrine neoplasms by regulating lipid metabolism and the mTOR signaling pathway." (PMID 40717587, 2025). "Studies have shown that in pancreatic neuroendocrine neoplasms, FABP5 activates the PI3K/Akt/mTOR signalling pathway, leading to enhanced lipid metabolism and cellular proliferation." (PMID 39928282, 2025). "In pancreatic neuroendocrine neoplasms, ALKBH5 over-expression was found to increase the expression of Fatty acid-binding protein 5 (FABP5) in an m6A-IGF2BP2 dependent manner, leading to disorders in lipid metabolism." (PMID 40428320, 2025).
allergic asthma (5 papers, 2019 to 2025). A asthma with a basis in a pathological type I hypersensitivity reaction. "in vivo suppression of FABP-5 exacerbates allergic asthma in a model of ovalbumin-induced allergic airway inflammation." (PMID 40099271, 2025). "Research indicates that in the pathogenesis of allergic asthma, fatty acid binding protein 5 (FABP5) is regulated under IL-4/IL-13 stimulation, modulating the metabolism of LCPUFAs, particularly the accumulation of oleic acid." (PMID 40735411, 2025). "Allergic asthma is aggravated by FABP-5 inhibition in vivo in an ovalbumin-induced allergic airway inflammation model." (PMID 37569407, 2023). "They determined that fatty acid binding protein 5 (FABP5) was increased in the sputum of patients with allergic asthma and showed the relationship of this protein with airway remodeling and inflammation." (PMID 33194371, 2020). "Interestingly, excessive oleic acid also aggravates allergic asthma by promoting M2 polarization, which is dependent on FABP-5." (PMID 37569407, 2023). "Notably, excess oleic acid worsens allergic asthma by promoting FABP-5-dependent M2 polarization." (PMID 40099271, 2025).
autoimmune disease (5 papers, 2015 to 2024). A disorder resulting from loss of function or tissue destruction of an organ or multiple organs, arising from humoral or cellular immune responses of the individual to their own tissue constituents. "FABP5 has been widely reported in autoimmune diseases such as multiple sclerosis, inflammatory neuronal remodeling, and DCs dysregulation." (PMID 38596682, 2024). "Inhibition of FABP5 triggers activation of the cGAS‐STING pathway, inducing IL‐10 production and promoting the inhibitory activity of Treg, thus attenuating autoimmune disorders." (PMID 38500390, 2024).
breast tumor (5 papers, 2014 to 2023). "As evidenced by immunohistochemistry, ATGL and FABP5 also had higher expression levels at the invasive front of the breast tumor, in where the adipocytes abound, compared to the central area in tissue specimens." (PMID 29914512, 2018). "Together, our results suggested that FABP5+ macrophages may be an emerging dangerous target cells in the breast tumor microenvironment in addition to the majority of macrophages that exert normal protective effects." (PMID 37021816, 2023). "Analysis of a qPCR array consisting of cDNA derived from samples of normal breast and various stages of human breast tumors (OriGene) showed that downregulation of KLF2 during disease progression is correlated with a marked decrease in the ratio of CRABP2 and FABP5 mRNAs." (PMID 26416422, 2015).
clear cell renal cell carcinoma (5 papers, 2020 to 2024). "In clear cell renal cell carcinoma, FABP5 binds transported fatty acids and their derivatives, thereby exerting a pro-proliferative role together with poor prognosis, while silencing FABP5 impairs of cell proliferation." (PMID 38653992, 2024).
dermatitis (5 papers, 2013 to 2026). An inflammatory process affecting the skin. "Among other functions, ether-linked lipids are a necessary precursor of PAF, and we observed increased PAF concentrations in FABP5-deficient animals with dermatitis." (PMID 41279180, 2025). "We found that Fabp5−/−Rag2−/− double knockout animals developed worse dermatitis than their Fabp5+/+Rag2−/− littermate controls FABP5-deficiency in Rag2−/− mice similarly resulted in an increase in skin-infiltrating neutrophils." (PMID 41279180, 2025). "Concordantly, we observe elevated PAF in FABP5-deficient mice with dermatitis and that depletion of basophils, a major source of PAF, is sufficient to ameliorate disease in these animals." (PMID 41279180, 2025). "Indicative of these functions, we found that dermatitis in FABP5-deficient animals was associated with increased endothelial leak, and neutrophils in the skin." (PMID 41279180, 2025). "Altogether these results suggest that regulation of PAF metabolism through an axis dependent on FABP5 and basophils controls alters dermatitis severity." (PMID 41279180, 2025). "FABP5 is found in circulation in naïve mice and the circulating concentration of FABP5 increases during dermatitis." (PMID 41279180, 2025). "Surprisingly, when treated with MC903, we observed that conditional deletion of FABP5 from neither keratinocytes nor myeloid cells was sufficient to recapitulate the exacerbated dermatitis observed in germline FABP5 KO mice." (PMID 41279180, 2025). "Here, we use a murine model of atopic dermatitis, to demonstrate that FABP5 is highly expressed in immune and epithelial cell lineages and that FABP5 protects against skin inflammation." (PMID 41279180, 2025). "Data from scRNAseq and FABP5HA immunofluorescence revealed that multiple cell types upregulate FABP5 expression during dermatitis." (PMID 41279180, 2025). "To test which cell types upregulate Fabp5 during dermatitis, we performed single cell RNA sequencing (scRNAseq) on cells isolated from skin of RAG2-KO mice treated with MC903 or vehicle control." (PMID 41279180, 2025). "Strikingly, Fabp5−/− mice displayed more severe dermatitis apparent in the increase in skin thickness over time and under histological examination." (PMID 41279180, 2025). "Together, these data suggest that FABP5 acts independently of the adaptive immune system to constrain dermatitis severity and limit neutrophil infiltration in the skin during AD." (PMID 41279180, 2025). "The observation that FABP5-deficient animals have altered concentrations of ether-linked lipids in circulation led us to reason that FABP5-deficient animals may exhibit altered PAF metabolism during dermatitis that contributes to the observed increase in disease severity." (PMID 41279180, 2025). "To definitively test the role of FABP5 during dermatitis, we created Fabp5−/− mice by excising the Fabp5 coding region on mouse chromosome 3." (PMID 41279180, 2025). "We hypothesized that inhibiting the major degrative enzyme of PAF would exacerbate dermatitis in WT mice and recapitulate the phenotype observed in FABP5 KO animals." (PMID 41279180, 2025). "For these reasons, we decided to test whether PAF metabolism was altered in dermatitis and could be further altered by FABP5." (PMID 41279180, 2025). "However, following MC903-induced dermatitis there was a significant increase in skin FABP5 concentrations in K14ΔFabp5 mice, though this was still significantly lower than FABP5 concentrations in the MC903-treated K14-cre control mice." (PMID 41279180, 2025). "The mechanism by which FABP5 modulates PAF concentration during dermatitis remains uncertain." (PMID 41279180, 2025). "Moreover, signaling via PPARδ-mediated pathways, mostly through Fabp5 upregulation, was mainly enhanced in allergen-induced dermatitis." (PMID 23977003, 2013). "Notably, in our mouse model, the Fabp5 vs. Crabp2 ratio was increased in allergen-induced dermatitis." (PMID 23977003, 2013).
dermatitis (continued). "Altogether, these results indicate that FABP5 is expressed and secreted by multiple cell types in vivo and suggest that FABP5 may ameliorate dermatitis through the regulation of tissue or systemic lipid metabolism rather than through its canonical role of controlling intracellular lipid metabolism." (PMID 41279180, 2025). "Furthermore, the increased ratio of Fabp5 vs. Crabp2 may indicate an up-regulation of the PPARδ pathway in allergen-induced dermatitis in addition to the altered RAR signaling." (PMID 23977003, 2013). "Congruent with this finding, we observed dramatically increased FABP5 transcript and protein levels in the skin of mice with MC903-induced dermatitis compared to vehicle treated controls." (PMID 41279180, 2025). "Together, these data demonstrate that multiple myeloid and non-immune cell types induce FABP5 expression in response to MC903-induced dermatitis." (PMID 41279180, 2025). "Notably, the ratio of Fabp5 vs. Crabp2 gene expression, both delivering ATRA to their respective cognate receptors, significantly increased in allergen-induced dermatitis." (PMID 23977003, 2013).
myeloma (5 papers, 2021 to 2025). "To establish potential clinical relevancy, we next tested for an association between FABP5 and MM in independent patient datasets using Multiple Myeloma Research Foundation (MMRF) CoMMpass and OncoMine." (PMID 36880649, 2023). "Our further analysis demonstrated that FABP5 dysregulation was in relationship with immune microenvironment of multiple myeloma, indicating that FABP5 was an underlying immunotherapeutic target for multiple myeloma." (PMID 34249967, 2021). "Following validation, FABP5 mRNA was a key risk factor of multiple myeloma." (PMID 34249967, 2021). "A recent study showed that patients with multiple myeloma, who have high levels of FABP5 in their tumors, have worse outcomes than patients with lower levels." (PMID 36880649, 2023). "A recent study found that targeting fatty acid binding proteins (FABPs), including FABP5, in MM reduced MYC signalling and induced apoptosis of myeloma cells, highlighting the association of aberrant lipid metabolism with MM." (PMID 37568580, 2023). "In the CoMMpass database, ~70% of myeloma patient cases exhibited moderate-to-high expression of FABP5 (defined as >10 counts)." (PMID 36880649, 2023). "Patients that have high FABP5 expression within their myeloma cells have worse outcomes and high FABP5 is seen in MM clinical subtypes that have a more aggressive phenotype." (PMID 36880649, 2023). "We found that myeloma cells treated with FABPi or with FABP5 knockout (generated via CRISPR/Cas9 editing) exhibited diminished proliferation, increased apoptosis, and metabolic changes in vitro." (PMID 36880649, 2023). "Among all dysregulated immune-related mRNAs, AEN, CD320, FABP5, and GPI were risk factors for multiple myeloma, while CXCL12, IGKC, NOD2, VCAM1, and WNT5A were protective factors for multiple myeloma." (PMID 34249967, 2021). "A positive correlation between FABP5 mRNA and B cells naïve was detected in multiple myeloma bone marrow specimens (r = 0.11, p = 0.015)." (PMID 34249967, 2021). "The relationships between FABP5 mRNA expression and infiltrations of immune cells were assessed in multiple myeloma bone marrow specimens." (PMID 34249967, 2021). "Both in the GSE6477 and GSE47552 datasets, FABP5 mRNA was up-regulated in multiple myeloma compared to normal bone marrow specimens (p = 0.042 and 0.002)." (PMID 34249967, 2021). "Myeloma cell proliferation also decreased with genetic knockout of FABP5, although FABP signaling compensation may have occurred via upregulation of FABP6." (PMID 36880649, 2023). "Taken together, FABP5 mRNA could be a promising therapeutic target as well as prognostic marker in multiple myeloma." (PMID 34249967, 2021). "After multiple dataset verification, FABP5 was a key prognostic factor for multiple myeloma." (PMID 34249967, 2021). "However, the prognostic value of FABP5 mRNA will be confirmed in a multicenter multiple myeloma cohort." (PMID 34249967, 2021). "Thus, in our future studies, we will validate the therapeutic effects of FABP5 mRNA therapy in multiple myeloma by experiments." (PMID 34249967, 2021). "Nevertheless, the biological roles of FABP5 remain indistinct in multiple myeloma." (PMID 34249967, 2021). "Combining above data, FABP5 mRNA was a key immune-related prognostic marker for multiple myeloma." (PMID 34249967, 2021). "Moreover, more experiments should be verified the functions of FABP5 in multiple myeloma progress and immune microenvironment." (PMID 34249967, 2021). "Nevertheless, the malignant roles of FABP5 mRNA remain undefined in multiple myeloma." (PMID 34249967, 2021). "Combining previous research, FABP5 mRNA might be a potential immunotherapeutic target of multiple myeloma." (PMID 34249967, 2021). "Correlation between FABP5 mRNA and immune cells was then analyzed in multiple myeloma." (PMID 34249967, 2021).
osteosarcoma (5 papers, 2023 to 2025). A usually aggressive malignant bone-forming mesenchymal neoplasm, predominantly affecting adolescents and young adults. "NSUN2 stabilizes FABP5 mRNA by inducing m5C modification, further promoting fatty acid metabolism in osteosarcoma cells." (PMID 41462962, 2025). "NSUN2 upregulated FABP5 expression by increasing FABP5 mRNA stability, promoting fatty acid metabolism in osteosarcoma cells and facilitating osteosarcoma progression." (PMID 41462962, 2025). "Animal models have validated that the inhibition of the NSUN2/FABP5 axis attenuates the prooncogenic effects of m5C modification in osteosarcoma, thus presenting novel avenues for osteosarcoma treatment." (PMID 38721006, 2024). "On the contrary, FABP5 also play a carcinogenesis role by promoting lipid metabolism in osteosarcoma." (PMID 37858219, 2023). "The FAO inhibitor etomoxir and FABP5 deficiency have proven effective in counterbalancing the impact of NSUN2 upregulation on FA metabolism and the proliferation, migration, and invasion of osteosarcoma 143b cells." (PMID 38721006, 2024).
atopic dermatitis (4 papers, 2021 to 2026). "In psoriatic and atopic dermatitis skin, FABP5 is primarily localized to the nuclei of suprabasal keratinocytes, suggesting efficient local production of PPARβ/δ ligands that sustain its activation." (PMID 41369331, 2025). "Previous reports identified Fatty acid binding protein 5 (FABP5) as a biomarker for atopic dermatitis, yet how FABP5 might contribute to disease pathogenesis is unknown." (PMID 41279180, 2025). "Notably, the expression of Ppard and Fabp5 is markedly increased in the epidermis of mouse models of lesional atopic dermatitis." (PMID 34298981, 2021). "However, FABP5 is also highly expressed in various immune cell populations, endothelial cells, and adipocytes, all of which could contribute to the pathology of atopic dermatitis." (PMID 41279180, 2025).
colon cancer (4 papers, 2015 to 2024). "After silencing FABP5 activity, a significant reduction in the invasive capacity of colon cancer cells (CRC) is observed." (PMID 32850012, 2020). "Retinoic acid (RA) has been reported to increase expression of pro-survival genes and tumor growth by activating PPARβ/δ in colon cancer in cells with high FABP5 relative to CARBPII, which in turn can modulate PI3K/Akt pathway." (PMID 25950950, 2015). "In the case of colon cancer, FABP5 contributes to its development by reducing p21 activity." (PMID 32850012, 2020).
heart failure (4 papers, 2018 to 2022). Inability of the heart to pump blood at an adequate rate to meet tissue metabolic requirements. "We have recently reported that mice doubly deficient for fatty acid binding protein 4 (FABP4) and FABP5 (FABP4/5DKO) develop heart failure under pressure overload by TAC30." (PMID 30104639, 2018). "Moreover, FABP5 has been observed to be enriched in classical monocytes of heart failure patients, suggesting that FABP5 contributes to monocyte activation." (PMID 35370940, 2022). "Metabolically active genes such as fatty acid binding protein 5 (FABP5) are highly enriched in classical monocytes from heart failure patients, whereas b-catenin expression was significantly higher in another functionally distinct monocyte subset (CD14++CD16+ intermediate monocytes)." (PMID 34926621, 2021). "Therefore, FABP5 upregulation may contribute to deep inflammatory signaling induction in the typical monocytes of patients with heart failure." (PMID 35252379, 2022).
lung adenocarcinoma (4 papers, 2021 to 2025). A carcinoma that arises from the lung and is characterized by the presence of malignant glandular epithelial cells. "For example, CCAT1 has been demonstrated to mediate the nuclear translocation of FABP5, subsequently promoting lung adenocarcinoma progression." (PMID 39928282, 2025). "For instance, FABP5 has been reported to promote tumor progression by mediating fatty acid metabolism and stabilizing PI3K/AKT/mTOR signaling in lung adenocarcinoma." (PMID 36792587, 2023).